TSC1 (TSC complex subunit 1)
Diseases named in the same sentence as TSC1 in open-access papers (continued):
Sharing a sentence is not in itself a finding about the gene and the disease.
angiomyolipoma (27 papers, 2012 to 2025). A neoplasm with perivascular epithelioid cell differentiation often associated with tuberous sclerosis. "Patients with TSC2 mutations had significantly earlier angiomyolipoma detection (13 vs. 23 years) and showed significantly higher rates of multiple and bilateral angiomyolipomas than those with TSC1 mutations." (PMID 38483608, 2024). "From a genetic point of view, angiomyolipomas frequently show loss of heterozygosity in TSC2 or TSC1." (PMID 34572815, 2021). "Tumors in TSC, including angiomyolipomas and renal cell carcinomas, develop after somatic “second hit” inactivation of the remaining wild-type allele of TSC1 or TSC2." (PMID 34680979, 2021). "The prevalence of angiomyolipomas was significantly higher in patients with TSC2 vs. TSC1 mutations (57.5 vs. 33%, p < 0.0001)." (PMID 33041968, 2020). "Our results indicate that therapeutic approaches for treatment of patients with angiomyolipoma should focus on the consequences of TSC2/TSC1 loss, including but not limited to mTOR activation." (PMID 27494029, 2016). "TSC2 mutations were predominant among patients in both trials and were present in nearly all subjects with angiomyolipoma in whom a mutation was identified (97%), whereas TSC1 mutations were rare in those subjects (3%)." (PMID 25782670, 2015). "mTOR was known to be involved in the pathogenesis of angiomyolipoma (both in syndromic and non-syndromic scenarios), but mutations in genes that regulate this pathway (TSC1, TSC2, and MTOR) were also rarely found in some common renal tumors, such as ChRCC, clear cell RCC, and papillary RCC." (PMID 37845471, 2023). "The loss of Tsc1 in mouse embryo NTs leads to the accumulation of NSCs, inhibition of differentiation, and increased oscillation of Hes1 and Rheb expression, consistent with our findings in angiomyolipoma cells." (PMID 29184052, 2017). "Consistent with extensive previous data and Knudson’s two-hit hypothesis, we identified biallelic inactivation of TSC2 or TSC1 in 30 of 32 angiomyolipomas and LAM tumors including point mutations, small indels, large genomic deletions, and copy neutral LOH." (PMID 27494029, 2016). "Therefore, we next determined whether the loss of Tsc1/2 blocks progenitor differentiation during mouse embryogenesis via a mechanism similar to that in angiomyolipoma cells." (PMID 29184052, 2017). "TSC-LAM results from mutations in genes TSC1 and TSC2, where it commonly manifests in the brain (e.g. seizures), renal (e.g. angiomyolipomas), and skin (e.g. lesions) divisions." (PMID 40196153, 2025). "As an exception, in tuberous sclerosis complex (mutation in TSC1, 9q34.13 or TSC2, 16p13.3), angiomyolipomas represent the typical lesions and are more frequent in females." (PMID 34572815, 2021). "Rates of multiple angiomyolipomas, bilateral angiomyolipoma, renal angiomyolipoma lesions of >3 cm were significantly higher in those with TSC2 mutations than those with TSC1 mutations." (PMID 33041968, 2020). "In general, TSC2 disease was more severe than TSC1, with more subependymal giant cell astrocytomas and angiomyolipomas, higher incidence of pharmacoresistant epileptic seizures, and more severe neuropsychiatric disorders." (PMID 29196670, 2017). "We employed a nestin or GFAP-Cre driver to remove the floxed Tsc1 allele from the NSCs and early and late neuronal progenitors, respectively, since both promoters are active in LAM and angiomyolipoma." (PMID 29184052, 2017). "Previous genetic studies have shown that angiomyolipomas arising in TSC patients occur due to biallelic inactivation of either TSC2 or TSC1." (PMID 27494029, 2016). "Somatic genetic alterations other than TSC1/TSC2 identified in 23 angiomyolipoma/LAM samples subject to tumor-normal paired exome sequencing." (PMID 27494029, 2016). "In these angiomyolipomas, we found consistent involvement of the TSC2 and TSC1 genes that are known to cause TSC, but very few (<5 on average) mutations elsewhere in the protein-coding regions." (PMID 27494029, 2016).
angiomyolipoma (continued). "Of the 13 children with high-risk angiomyolipomas, 8 (62%) had TSC2 mutation, and 1 (7.7%) had TSC1 mutation, while others had NMI or unknown genetics." (PMID 38483608, 2024). "The TSC1 and TSC2 genes behave as classical tumor suppressor genes, with germline loss-of-function mutations accompanied by somatic loss-of-function of the remaining wild-type allele in tumors including angiomyolipomas." (PMID 34680979, 2021). "It is unknown whether additional genetic events, beyond loss of TSC1 or TSC2, contribute to angiomyolipoma development, particularly in large tumors requiring surgical resection." (PMID 27494029, 2016). "Our findings suggest that angiomyolipomas fit this general model of pediatric tumor development, with few somatic mutations and a single critical target of inactivating mutation (in the case of angiomyolipoma, this is usually TSC2 and less commonly TSC1) that initiates and drives tumor development." (PMID 27494029, 2016). "LAM and angiomyolipoma also are seen at high frequency in patients with tuberous sclerosis complex (TSC), a disorder caused by mutation of TSC1 or TSC2, for which the gene products negatively regulate mTORC1 through inhibition of the mTOR kinase activator, RHEB." (PMID 22943457, 2012). "We used a genetic strategy for cell-specific depletion of Tsc1 in the mouse embryo NT because expression of ID1 and ID3 was suppressed in angiomyolipoma cells in N-medium, Id proteins as well as high level of Hes1 prevent neurogenesis in NT50, 51, and Id3 and Hes1 are regulated by Notch154." (PMID 29184052, 2017).
subependymal giant cell astrocytoma (26 papers, 2015 to 2026). A benign, slowly growing tumor (WHO grade I) typically arising in the wall of the lateral ventricles and composed of large ganglioid astrocytes. "TSC2 variants were associated with more severe phenotypes, including subependymal giant cell astrocytoma, whereas TSC1 variants typically presented with milder manifestations." (PMID 42249814, 2026). "Three cases showed TSC2 missense mutations and an additional one truncating TSC1 mutation, but a diagnosis of subependymal giant cell astrocytoma was discarded in these cases." (PMID 32642724, 2020). "Subependymal giant cell astrocytomas typically arise in patients with TSC1/2 mutation." (PMID 36566461, 2023). "This is the case of tuberous sclerosis 1/hamartin (TSC1) or tuberous sclerosis 2/tuberin (TSC2) mutations occurring in subependymal giant cell astrocytomas, as well as H3 histone family member A/B (HIST1H3A/B) and activin receptor type 1 (ACVR1) mutations in diffuse intrinsic pontine gliomas." (PMID 31968687, 2020). "The diagnosis was confirmed by DNA methylation profiling, which assigned the tumor to the methylation class “subependymal giant cell astrocytoma with TSC1/TSC2 alterations” with a calibrated score of 0.95." (PMID 39492623, 2025). "Structural abnormalities similar to subependymal nodules (SEN) and subependymal giant cell astrocytomas (SEGA) occur in mice with TSC1 knockdown in NSCs at various developmental stages." (PMID 39901197, 2025). "Subependymal nodules (SEN) appear deeper within the brain, affecting 68% and 78% of TSC1 and 2 patients in their respective groups, and subependymal giant cell astrocytoma (SEGA) were detected with even smaller prevalence at 32% and 26%, respectively." (PMID 35440050, 2022). "In the PNET dataset, 3.3% of cases harboured TSC1 or TSC2 mutations conferring sensitivity to the mammalian target of rapamycin (mTOR) inhibitor, everolimus, currently approved for renal angiomyolipomas and giant cell astrocytomas." (PMID 35849877, 2022). "For example, patients with tuberous sclerosis complex (TSC), caused by mutations in the tumor suppressor genes TSC1 or TSC2 leading to mTOR hyperfunction, show heterogeneity of benign tumors and cellular dysplasia in multiple organs, including astrocytomas and cortical tubers in the brain." (PMID 27655340, 2016). "TSC1/2 are known tumor suppressors, loss of function mutations in these genes cause tuberous sclerosis complex (TSC), a fairly frequent tumor syndrome that includes the development of subependymal giant cell astrocytomas (SEGAs)." (PMID 25993328, 2015). "No TSC1 or TSC2 mutations were identified in any of the cases, suggesting that gangliogliomas are also genetically distinct from the majority of subependymal giant cell astrocytomas." (PMID 29880043, 2018). "He underwent gross total resection; the tumor pathology was consistent with subependymal giant cell astrocytoma, WHO Grade I. Germline TSC1/TSC2 gene sequencing was negative." (PMID 36980535, 2023).
Renal cyst (25 papers, 2012 to 2025). A fluid filled sac in the kidney. "Patients with tuberous sclerosis complex (TSC) develop renal cysts and/or angiomyolipomas (AMLs) due to inactive mutations of either TSC1 or TSC2 and consequential mTOR hyperactivation." (PMID 39333852, 2024). "Examination of murine models of renal cystic disease associated with either Tsc1 or Tsc2 directly or indirectly has revealed that cyst development is linked to particular nephron segments, with all tubular segments implicated in Tsc cyst formation." (PMID 39201746, 2024). "Using a mouse model of renal cystic disease caused by the ablation of the Tsc1 gene in kidney principal cells, we identified multiple alterations in the metabolome and transcriptome of Tsc1 KO compared to Wt mice." (PMID 36142537, 2022). "In contrast, loss of Tsc1 or Tsc2 enhances cilia length in mouse embryonic fibroblasts (MEFs), and intriguingly, clinically there is a relatively low frequency of renal cyst and RCC formation in TSC patients." (PMID 23369289, 2013). "Multiple renal cysts are infrequently observed in the general populace but may be present in TSC patients harboring mutations in TSC1 or TSC2 or as part of contiguous gene deletion syndromes affecting the TSC2 and PKD1 genes." (PMID 39201746, 2024). "Expression of p-S6 might therefore be expected in some malignant tissues and, indeed, marked expression has been illustrated in tumour cells lining some renal cysts in mice with mutation in the gene Tsc1 that forms part of the tuberous sclerosis complex." (PMID 23105973, 2012). "These mice developed renal cysts that were primarily composed of A-IC cells that express both TSC1 and TSC2." (PMID 40243914, 2025). "In fact, examination of renal cysts in mouse models of TSC indicates that they are composed of cells that express both TSC1 and TSC2." (PMID 40243914, 2025). "Our published studies demonstrate that the knockout of Foxi1 in Tsc1 KO mice completely abrogates the development of renal cysts in these animals." (PMID 38731991, 2024). "The examination of renal cysts in Tsc1 KO mice revealed the predominance of proliferatively active A-IC cells in the cystic epithelium." (PMID 38731991, 2024). "The tubular epithelium of renal cysts in Tsc1 KO mice showed a predominant and widespread labeling with H+-ATPase on their apical membrane and a paucity of AQP2 labeled cells." (PMID 38731991, 2024). "In contrast, the ablation of Tsc1 in the principal cells (PCs) of the renal-collecting duct leads to substantial expansion of A-IC cells in the epithelium of renal cysts." (PMID 38731991, 2024). "The studies that are discussed in this review article demonstrate that in TSC renal cysts, A-IC cells that express both TSC1 and TSC2 constitute the cyst epithelium, and that FOXI1 plays a critical role in the process of cystogenesis." (PMID 38028758, 2023). "We have previously shown that mTORC1 inhibition during pregnancy alleviates cystic kidney disease in Tsc1 KO offspring by inhibiting the mTORC1 pathway and reducing the inflammatory response." (PMID 37290438, 2023). "The epithelium of renal cysts in Tsc1 KO mice is primarily composed of proliferatively active, H±-ATPase-expressing A-IC." (PMID 36142537, 2022). "The combined renal metabolome and transcriptome alterations observed in these studies correlate with the unregulated growth and predominance of genotypically normal A-intercalated cells in the epithelium of renal cysts in Tsc1 KO mice." (PMID 36142537, 2022). "Our results show that the inactivation of Tsc1 leads to both hyper-proliferation and loss of OCD that, together, lead to the onset of a cystic kidney phenotype." (PMID 32581239, 2020). "Complete ablation of Tsc1 in tubular cells leads to robust mTORC1 activation and kidney cystic disease." (PMID 32404875, 2020).
Renal cyst (continued). "A number of tumor suppressor genes that have established roles in renal tumorigenesis, namely VHL, TSC1, TSC2 and FLCN, also predispose to renal cyst formation, a common hallmark of ciliopathy syndromes." (PMID 23369289, 2013). "This becomes more apparent considering that the renal cyst epithelia in mice with cell-specific knockout of Tsc1 or Tsc2 genes in principal cells (PCs) or pericytes are almost entirely composed of A-ICs that express both TSC1 and TSC2." (PMID 40243914, 2025). "The principal cell-specific Tsc1-knockout (Tsc1KO) mouse model was used to determine the EV shuttle factors and the role of EVs isolated from the kidneys and kidney explants of Tsc1KO mice in renal cystic disease." (PMID 40243914, 2025). "In addition, PTCs are the primary source of cells responsible for TSC renal cyst development in the Tsc1 KO mice." (PMID 37290438, 2023). "Loss of such a compensatory mechanism may also explain why deletion of FNIP1 synergized with TSC1 deletion to activate mTOR and subsequently resulted in accelerated renal cyst formation in mice." (PMID 35883484, 2022). "This could explain the finding of renal cyst formation in TSC1+/− mice, as well as provide insight into the pro-migratory phenotype seen only in TSC2−/− MEFs." (PMID 35883484, 2022). "Fnip1Tsc1 double-null mice developed large cystic kidneys (kidney/brain ratio mean 1.79) by 4 weeks of age whereas Tsc1 null mice had normal appearing kidneys at 4 weeks, and did not develop cystic kidneys of comparable kidney/brain weight ratio as Tsc1Fnip1 double null mice until ~10 weeks of age." (PMID 29897930, 2018). "A case with separate TSC1 and PKD2 mutations had a very modest cystic phenotype, probably due to the relatively mild disease in PKD2 compared to PKD1 and because TSC1 mutations are rarely associated with renal cysts." (PMID 26077033, 2015). "Hartman found that Rapamycin enhanced cilia formation in TSC1 and TSC2 null cells and concluded that the efficacy of mTOR inhibitors on renal cystic disease in patients carrying a TSC mutation or PKD1/TSC2-CGS may differ from its efficacy in ADPKD." (PMID 26077033, 2015). "In those with liver cysts, 26/80 had no renal cysts or a TSC1 mutation." (PMID 35292049, 2022). "Furthermore, our results indicate that the phospho-S6 labeling in 47-day-old Tsc1/Car2 dKO mice is significantly reduced in comparison to time-matched WT mice, suggesting that Car2 deficiency and reduced A-IC cell numbers delay cyst formation in our model of TSC renal cystic disease." (PMID 38731991, 2024). "Kidney cysts are usually composed of cells that express intact TSC1 and TSC2 proteins in both mouse models, as well as in humans with TSC renal cystic disease." (PMID 38028758, 2023). "Cystic kidney disease is the second most frequent renal manifestation of TSC and can be triggered by the biallelic inactivation of TSC1/TSC2 alone or as the result of deletion events that also affect the PKD1 locus located adjacently in chromosome 1646." (PMID 34764250, 2021). "In contrast, this same difference is not observed in the case of renal cysts, where prevalence amongst TSC1 and TSC2 patients is almost equal at 27% and 29%, respectively, an insignificant difference at p < 0.05 (Z = −0.18, df = 1, p = 0.86)." (PMID 35440050, 2022). "Tsc1 haploinsufficiency without mTOR activation was shown to lead to renal cyst formation in TSC1+/− mice." (PMID 35883484, 2022). "However, unlike the Tsc1/Foxi1 dKO mice, the Tsc1/Car2 dKO animals develop severe renal cystic disease as they age." (PMID 38731991, 2024). "Similarly, loss of tumor suppressor genes such as TSC1 and TSC2 is not always accompanied by the development of renal cysts and overgrowth." (PMID 28353628, 2017).